INS (insulin)
Diseases named in the same sentence as INS in open-access papers (continued):
Sharing a sentence is not in itself a finding about the gene and the disease.
tumor (continued). "Of interest, insulin sensitivity has shown to be restored after surgical removal of the tumor, showing that the tumor may be the underlying cause of IR." (PMID 32230855, 2020). "Treatment with insulin abrogated the tumor-suppressive effect associated with these therapies." (PMID 33604295, 2020). "In our study, metabolic pathway analysis further revealed significant perturbation of glycolytic, gluconeogenic, fructose, galactose, pyruvate and creatine metabolism in HCCs of TSOD mice, closely associated with L-arginine accumulation and increased insulin sensitivity of tumor cells." (PMID 33092030, 2020). "Accordingly, caCers may find use in dissecting the causal roles of ceramides in apoptosis, as tumor suppressors, and as antagonists of insulin signaling." (PMID 30720434, 2019). "This is due to the notable reductions in GH and IGF-1 after tumor debulking, whether the tumor is totally or partially resected, and will cause decreased IR and elevated insulin sensitivity, thus gradually easing the IR-induced β-cell hyperfunction." (PMID 31736874, 2019). "The authors speculated that this was associated with unusual autonomy of insulin secretion by tumor cells." (PMID 29166433, 2019). "It is possible that the anti-tumour activity of sFRP4 in vitro maybe associated with inhibition of the insulin/IGF-1 pathway through AMPK activation." (PMID 29385093, 2018). "For example, food intake was not determined as animals were group-housed, and it remains unclear how parameters associated with glucose tolerance, including fed and fasted insulin and glucose levels, or the glucose-ketone index, correlate with tumour burden." (PMID 30189621, 2018). "Improved insulin sensibility, lower glucose and insulin levels and/or reduced insulin secretion stimulated by glucose may be implicated in this tumor attenuation." (PMID 29867528, 2018). "It is well-known that excess body fat is associated with the elevated production of insulin, which is a mitogenic stimulation factor that may enhance tumor growth by increasing free insulin-like growth factor-I (IGF-I)." (PMID 28389625, 2017). "In addition to the improvement of insulin sensitivity, the promotion of weight loss, and other systematic effects, metformin has tumor-cell specific effects." (PMID 27903961, 2017). "It is possible to reverse the effect of IGF1 by reducing the levels of insulin and insulin-binding protein, which may be the mechanism underlying its anti-tumor proliferative effects." (PMID 29241458, 2017). "Injectable insulin use may interfere with pro-inflammatory cytokines’ production and, thus, play a role in the activation of tumor-associated macrophages - a process mainly influenced by inflammatory C–C chemokines." (PMID 28289694, 2017). "Mechanistically, we provide functional evidence that activation of SIKs promotes Yki-dependent Wg-activation and reveal a SIK-Yki-Wg-InR axis as a key feed-forward signaling pathway that underlies evasion of insulin resistance and promotion of tumor growth in diet-enhanced Ras/Src-tumors." (PMID 26573956, 2015). "The enhanced tumor growth in the leucine-supplemented control group cannot be explained by changes in mTOR signaling in the tumor, but was associated with greater glucose availability (reduced fasting insulin levels and diminished glucose clearance)." (PMID 24685128, 2014). "But, based on the results of our study, we could not confirm that insulin glargine in comparison to other types of insulin causes faster tumor progression." (PMID 24131755, 2013). "Insulin-independent growth of PIK3CA H1047R-mutated tumor cells is inhibited by metformin in vitro." (PMID 23986086, 2013). "Thus, although insulin has direct, isolated actions on tumour growth, changes in glucose metabolism predispose changes in insulin signaling." (PMID 20182531, 2010).
tumor (continued). "Nonetheless, when considering genes that may encode novel therapeutic targets of both tumour insulin-expressing cell populations, the small number of genes ubiquitously expressed and upregulated in both clusters included COX7A2L (also known as COX7RP and SCAF1), with a mean 27-fold upregulation." (PMID 40438247, 2025). "This variability highlights the challenges of using PBMC-derived biomarkers in the context of PDAC and suggest that, although INS mRNA expression may reflect systemic metabolic changes associated with the disease, it cannot be entirely linked to tumor-specific gene expression in this study." (PMID 40699634, 2025). "Reduced adiponectin levels may enhance insulin signaling, which is associated with tumor growth." (PMID 40386557, 2025). "Postoperative weight gain may be related to invasive tumor treatment, which damages the paraventricular nucleus and the suprachiasmatic nucleus, leads to loss of satiety, and inhibits the interaction of leptin, insulin, and intestinal hormones." (PMID 37324266, 2023). "However, the current single secreted biomarkers for pancreatic NETs, such as gastrin, insulin and chromogranin A (CgA), have limited usefulness for diagnostic or prognostic purposes, owing to the complexity and diversity of multiple tumour development and varying responses to different therapies." (PMID 35900839, 2022). "In addition, insulin is implicated in tumorigenesis and tumor development." (PMID 34034636, 2021). "In addition, direct tumor effects of PNENs may cause the obstruction of the pancreatic duct and promote atrophy of pancreatic parenchyma, ultimately affecting insulin secretion." (PMID 33424776, 2020). "Therefore, here we hypothesise that metformin could decrease the inhibitory effect on insulin signalling in muscle tissue caused by tumour growth." (PMID 27388367, 2016). "However, due to a relatively short follow up time in the epidemiological studies, it cannot be excluded that diabetic patients with pre-neoplastic lesions might be at higher risk of developing an invasive tumour when given a specific insulin treatment." (PMID 26242987, 2015). "Because the binding of insulin to its receptors activates the PI3K/AKT/mammalian target of rapamycin (mTOR) signaling cascade, activating mutations in the PIK3CA oncogene may determine tumor response to DR-like pharmacological strategies targeting the insulin and mTOR pathways." (PMID 23986086, 2013). "Consequently, tumor cells with loss of SOCS6 may have increased activation of insulin and KIT-signaling resulting in uncontrolled growth." (PMID 22363434, 2012). "Importantly, we also identify a novel gene module within the insulin growth factor signalling pathway, alteration of which may predispose the tumour to metastasize." (PMID 20673354, 2010). "The insulin-positive cells showed significant clustering in 7 out of 13 tumours (R < 1 and P < 0.05)." (PMID 41488993, 2026). "The production of both proteins takes place inside the tumour cells, as insulin transcripts and GLP-1R transcripts are found in the TCGA cohort." (PMID 41488993, 2026). "In the tumours, we found that cells expressing insulin were present in the cytoplasm and GLP-1R in the membrane, with a frequency of 2.59 and 1.34%, respectively." (PMID 41488993, 2026). "Overall, our findings suggest that PDX1 plays a tumor-promoting role in human PCa cells by influencing expression of metabolites in insulin, inflammatory, and epithelial-mesenchymal transition (EMT) signaling pathways." (PMID 41955005, 2026). "Studies have shown that deletion of CES3 reduces plasma triglyceride (TG), fatty acid, and cholesterol levels, improves insulin sensitivity, and reduces tumor weight in tumor-bearing mice." (PMID 41438579, 2026). "In two tumours, we found deposits of insulin, 60–70 μm in diameter, which we suggest naming insulin bodies." (PMID 41488993, 2026).
tumor (continued). "Intraoperative portal venous insulin levels declined from 102 μU/mL before resection to 10 μU/mL before closure, confirming the complete tumor removal." (PMID 41783329, 2026). "Generally, the release from tumours with ectopic hormone production often lacks normal release control, also shown in insulin-producing tumours." (PMID 41488993, 2026). "We show that tumor-induced factors involved in inflammation (unpaired 3/ Interleukin-6-like) and reduced insulin signaling (ImpL2/ Insulin Growth Factor Binding Protein) decrease NPF (Neuropeptide F/ Neuropeptide Y) in the brain prior to organ wasting." (PMID 41792134, 2026). "Next, we summarize findings from preclinical and human studies demonstrating that cold exposure reduces serum lipid levels, enhances insulin sensitivity and glucose homeostasis, modulates immune responses, and inhibits tumor growth." (PMID 41947493, 2026). "It was reported rare cases of NICTH previously, patients have presented with decreased levels of insulin and C‐peptide in the tumor, along with excessive secretion of insulin‐like growth factor‐2 (IGF‐2)." (PMID 40550558, 2025). "PanNETs represent a heterogeneous group of tumours, presenting either as hormonally active tumours (producing gastrin, insulin, glucagon, somatostatin, vasoactive intestinal peptide or growth hormone-releasing hormone) or as non-functioning tumours." (PMID 39949334, 2025). "For instance, enriching SCFA-producing bacteria can improve insulin sensitivity and exert anti-tumor effects, illustrating a single mechanism with dual impact." (PMID 41374093, 2025). "GLP-1 RAs improve systemic glucose homeostasis and reduce circulating insulin levels, potentially disrupting insulin/IGF-1 signalling pathways frequently co-opted by tumour cells." (PMID 41300804, 2025). "mTOR is a serine/threonine kinase that plays a role in tumor growth, angiogenesis, insulin resistance, fat creation, and other cellular processes, as well as in metabolism." (PMID 39823500, 2025). "The expression level of sirtuin genes related to energy metabolism, apoptosis, tumor suppress, insulin secretion, and others was significantly changed." (PMID 41304476, 2025). "Considering disease structural progression and the difficulties in controlling the insulin production by the tumor, sunitinib was stopped and other therapeutic options were pursued." (PMID 41561059, 2025). "Unhealthy obese WAT affects circulating levels of free fatty acids and factors like leptin, adiponectin, and insulin, altering systemic lipid metabolism and inducing inflammation that supports tumor growth." (PMID 39496581, 2025). "In metastatic or unresectable cases, cytoreductive strategies, including debulking surgery and liver-directed therapies like transarterial embolization or ablation, are employed to reduce tumor burden and insulin output." (PMID 40647278, 2025). "In another study, a mitoxantrone-insulin conjugate was synthesized and characterized, in which the in vitro stability, in vivo biodistribution, tumor-targeting properties, and pharmacokinetics were studied in mice bearing H22 hepatocarcinoma." (PMID 40430034, 2025). "There were fewer differences between primary tumours in insulin-expressing cells (~ 600 DEGs) with only ~ 40 DEGs in the INS+ population between the two patients." (PMID 40438247, 2025). "In short, we position UA as a microbiome-derived molecule with bidirectional actions on tumor biology and insulin resistance, warranting rigorous clinical interrogation." (PMID 41374004, 2025). "Although Fen is widely used due to its comparatively low toxicity, it changes the metabolism of tumor cells, especially the insulin signaling pathway, and potentially affects chemotherapy resistance." (PMID 40070568, 2025).
tumor (continued). "Based on the suspected tumor type, laboratory tests commonly assess hormone levels such as insulin, gastrin, glucagon, vasoactive intestinal peptide (VIP), and somatostatin to identify functioning PANNETs." (PMID 40427145, 2025). "Recently, it has been shown that insulin treatment induced the downregulation of miR-27a-3p expression in human granulosa-like tumor cell line." (PMID 40257717, 2025). "In a tumor context, hypoxia, local insulin resistance, and even patterns of immune cell infiltration often shape outcomes more decisively than any genotype." (PMID 41010968, 2025). "Our previous work identified several tumor-secreted cytokines, including ImpL2, Upd3, and Pvf1, that disrupt insulin, JAK-STAT, and PDGF/VEGF signaling, respectively, in various host tissues in Yki flies." (PMID 40832336, 2025). "Among these, PDAC has the strongest correlation with new-onset diabetes (NOD), as tumor-related metabolic disruptions can drive insulin resistance and β-cell dysfunction." (PMID 40487412, 2025). "The PI3K pathway is an insulin-related pathway that promotes tumor development by altering glucose availability, while the Wnt pathway is inhibited by thyroid hormone receptors, resulting in tumor suppression." (PMID 41388389, 2025). "Physical activity positively influences various physiological aspects that affect tumor growth, including insulin and glucose metabolism, immune function, inflammation, sex hormones, oxidative stress, genomic instability, and myokines." (PMID 41178954, 2025). "Consistent with this, across the different cell types examined, the insulin-expressing tumour cells had the greatest proportion of cells in S phase, with the highest being a population of insulin-expressing cells in the metastasis." (PMID 40438247, 2025). "Clinically, the high prevalence of GCGR expression in pNET tissues and its inverse correlation with tumour grade, alongside the reduced GLP-1R expression, point to disrupted insulin–glucagon signalling in tumour progression." (PMID 40649254, 2025). "This suggests that the physiologic levels of insulin are critical to sustain tumor growth and that increased glucose availability alone cannot compensate." (PMID 40371988, 2025). "The researchers also revealed that the tumour-slowing effect was insulin-dependent, and restoring high insulin levels reversed the drug’s effects." (PMID 41471707, 2025). "We report that AKT(T308) is positively associated with plasma insulin levels in LLC fast mice and rpS6 was negatively associated with tumour growth rate." (PMID 40931444, 2025). "The relentless tumor progression highlights the pressing need for novel and more effective therapeutic options in the management of advanced insulin-secreting pNETs." (PMID 41561059, 2025). "It lowers bioavailable estrogens through increased SHBG, improves insulin sensitivity, decreases pro-inflammatory cytokines, and enhances antioxidant defenses, collectively creating a less favorable environment for tumor development and progression." (PMID 40731797, 2025). "Our study is the first to reveal the impact of Fen on altering tumor cell metabolism, especially in the insulin signaling pathway." (PMID 40070568, 2025). "Elevated insulin drives tumor proliferation and metabolic reprogramming through IRs or enhanced IGF‐1 activity, particularly in breast, colorectal, and prostate cancers." (PMID 41267926, 2025). "Metformin, a first-line therapy for T2DM, improves insulin sensitivity and has demonstrated potential anti-tumor activity in experimental models by inhibiting the mammalian target of rapamycin (mTOR) signaling pathway." (PMID 40764810, 2025). "It has also been demonstrated that activation of the insulin/IGF-1 signaling pathway induces tumor cell growth and proliferation." (PMID 40427517, 2025).
tumor (continued). "Mechanistically, tumor burden positively correlated with postprandial insulin levels (r = 0.62, p < 0.01), hepatic interleukin-6 (IL-6) expression (r = 0.58, p < 0.05), and liver cholesterol accumulation (r = 0.71, p < 0.001)." (PMID 41398969, 2025). "Caloric restriction and intermittent fasting have demonstrated benefits in improving insulin sensitivity and reducing tumor growth." (PMID 40387523, 2025). "Our prior investigations revealed that dampening insulin signaling by restricting glucose uptake stymied SCC tumor growth, chiefly by disrupting glucose metabolism and suppressing the PI3K/AKT axis." (PMID 40371988, 2025). "Consistently, the survival benefit of exercise was most evident in tumors with low IRS-1 expression, suggesting reduced tumor sensitivity to insulin signaling." (PMID 41178954, 2025). "These interactions span key pathways related to immune evasion, insulin resistance, oxidative stress, inflammation, uncontrolled apoptosis, and tumor proliferation, all of which are central to the pathogenesis of chronic liver disease." (PMID 41009545, 2025). "Its adaptor function in insulin-dependent PIP3 production in skeletal muscle is consistent with its role as an inhibitor of the tumour suppressor Pten." (PMID 40764335, 2025). "In xenograft models, sapanisertib, serabelisib plus paclitaxel/insulin supressing diet achieved complete inhibition of tumour growth/tumour regression." (PMID 40360883, 2025). "This review synthesises clinical and experimental evidence into an islet-centric view in which tumour-derived signals and microenvironmental changes impair β-cell insulin secretion and disrupt α- and δ-cell regulation." (PMID 41226286, 2025). "It has been shown to suppress tumor growth, improve insulin sensitivity, and protect against the adverse effects of chronic diseases, such as cardiovascular complications and neurodegenerative conditions." (PMID 40585493, 2025). "Adiponectin promotes insulin sensitivity and cell proliferation and acts as a protective factor against tumor progression and exerts its function by binding to the AdipoR1 and AdipoR2 receptors." (PMID 40430851, 2025). "The stromal microenvironment actively supports tumor progression through complex interactions between tumor and stromal cells via paracrine signaling pathways involving insulin and IGF-1 receptors." (PMID 40699634, 2025). "These pathways are frequently dysregulated in tumor cells and provide a mechanistic link between insulin/IGF1 and the onset and progression of cancer." (PMID 40430851, 2025). "When intraoperative tumor localization was difficult, they suggested obtaining pancreatic vein sampling for insulin analysis or distal pancreatectomy." (PMID 39740410, 2025). "The two insulin-expressing clusters that were identified within each canine tumour can be described by their strong differences in transcription factor expression." (PMID 40438247, 2025). "For instance, insulin resistance in adipose and liver tissues correlates with elevated circulating levels of insulin and glucose, which indirectly fuels tumor progression." (PMID 40906088, 2025). "There is a substantial overlap between the top-10 chemical neighbors lists for neoplasms and insulin, with eight chemicals appearing in both lists." (PMID 41402869, 2025). "The combination of prolonged estrogen exposure and insulin resistance creates a permissive environment for tumor development." (PMID 40989682, 2025). "Dorzagliatin’s ability to enhance insulin regulation is instrumental in preventing the hyperactivation of this pathway, thereby facilitating more effective suppression of tumor growth by PI3Ki." (PMID 40573322, 2025). "In contrast, COX7A2L was one of a few genes ubiquitously expressed and significantly upregulated (> 20-fold) in both insulin-expressing tumour populations compared to other captured populations." (PMID 40438247, 2025).